CTCF (CCCTC-binding factor)
Diseases named in the same sentence as CTCF in open-access papers (continued):
Sharing a sentence is not in itself a finding about the gene and the disease.
breast carcinoma (continued). "For instance, CTCF overexpression was previously reported in breast cancer, cervical cancer, ovarian cancer, and hepatocellular carcinoma and is often related to tumor features with adverse prognostic impacts." (PMID 33665169, 2020). "A multifunctional transcription factor, CTCF plays a role in many types of cancer, including breast cancer, via different mechanisms." (PMID 32850701, 2020). "CTCF overexpression has been identified in breast cancer, cervical cancer, ovarian cancer, and hepatocellular carcinoma." (PMID 33665169, 2020). "Higher expression CTCF in breast cancer cells has been shown to provide a survival advantage by inhibiting apoptosis." (PMID 31245293, 2019). "Classification of primary breast cancer RNASeq data based on high/low CEBPB/REST/CTCF revealed that, KRT5, KRT14 and KRT17 mRNAs were significantly upregulated in CEBPBhigh and CTCFlow tumors." (PMID 30335837, 2018). "To determine if CTCF also inhibits metastasis and invasion in breast cancer, we performed wound healing and Transwell assays in vitro." (PMID 29212169, 2017). "We reported, for the first time, that CTCF knockdown increased cell migration and invasion in breast cancer cells." (PMID 29212169, 2017). "Both the T47D and 435 cell lines appear to contain only the 130kDa form of CTCF, which is perhaps unsurprising given that these are advanced breast cancer cell lines." (PMID 29029387, 2017). "The results showed that CTCF expression in human breast cancer cells and tissues was significantly lower than that in normal breast cells and tissues." (PMID 29212169, 2017). "Increased CTCF has been observed in some cancers, including breast cancer, ALL and invasive cervical cancer, and thus, in these contexts, CTCF possesses oncogenic features." (PMID 28977939, 2017). "Taken together, these results suggested that CTCF functions as a tumor suppressor and plays a pivotal role in breast cancer progression." (PMID 29212169, 2017). "Our findings indicated a tumor suppressor role of CTCF in the development and progression of breast cancer." (PMID 29212169, 2017). "Western blotting analysis showed that CTCF was downregulated in the three breast cancer cell lines examined." (PMID 29212169, 2017). "Our experiments imply an important role for CTCF in inhibition of NF-kB over-activation in breast cancer occurrence and metastasis." (PMID 29212169, 2017). "Taken together, these findings provided strong evidence that the downregulation of CTCF enhances breast cancer progression." (PMID 29212169, 2017). "We first examined CTCF expression in human breast cancer cell lines MCF-7, SKBR3, and MDA-MB-231 as well as normal breast cells MCF-10A." (PMID 29212169, 2017). "The present study provides a new insight into the tumor suppressor roles of CTCF in breast cancer development and suggests that the CTCF/NF-κB pathway is a potential target for breast cancer therapy." (PMID 29212169, 2017). "Taken together, CTCF acts as a tumor suppressor in breast cancer by inhibiting the activation of NF-κB (p65) and its target genes." (PMID 29212169, 2017). "CTCF mediates the binding of the unmethylated imprinting control region to the IGF2 promoter region in the breast cancer MCF7 cell line." (PMID 29149895, 2017). "The results showed that higher CTCF mRNA expression in patients with breast cancer correlated with an improvement in relapse-free survival." (PMID 29212169, 2017). "In this study, we showed that CTCF protein levels, but not mRNA expression, were downregulated in breast cancer cells, indicating that post-transcriptional CTCF regulation plays an important role in breast cancer cells." (PMID 29212169, 2017). "Analysis of the publicly available datasets (Kaplan-Meier Plotter) revealed a correlation between a decreased CTCF mRNA level and poor prognosis in breast cancer patients." (PMID 29212169, 2017).
breast carcinoma (continued). "The expression of CTCF was analyzed in only three breast cancer cell lines; therefore, further analysis was carried out to verify the difference in CTCF expression using normal and tumor breast tissues." (PMID 29212169, 2017). "In this study, we examined CTCF expression in breast cancer tissues and cell lines, and analyzed the correlation between CTCF expression and various clinicopathological parameters." (PMID 29212169, 2017). "CTCF is recognized as a putative tumor suppressor, and the disruption of CTCF promotes the development of colorectal cancer, prostate cancer and breast cancer." (PMID 28977939, 2017). "To investigate the details of an association between DNA methylation and CTCF in DLL4 gene regulation, we treated another breast cancer cell line, MDA231, which has a silenced DLL4 gene expression, with increasing concentrations of 5′-aza-dC for 3 days." (PMID 27542210, 2016). "Concerning the role of CTCF in microRNAs, a recent report showed that the miR-125b1 is aberrantly silenced by DNA methylation in breast cancer cells." (PMID 26983574, 2016). "MiR-125b expression is decreased in breast cancer, partly, through CTCF dissociation from its promoter region." (PMID 26983574, 2016). "Recently, CTCF was found to be involved in the regulation of miR-125b1, miR-375, and the miR-290 cluster in breast cancer cells and stem cells." (PMID 25707768, 2015). "CTCF knock-down triggers apoptosis in breast cancer cells, whereas over-expression of CTCF partially protects cells from Bax-induced apoptosis; CTCF mRNA knock-down promotes stress-induced apoptosis in human corneal epithelial cells." (PMID 24393203, 2014). "Previous study reported such a controversial role of CTCF in breast cancer cells and human corneal epithelial cells, which strongly support our findings." (PMID 24393203, 2014). "CTCF, also located on 16q22.1, has been found to act as a tumor suppressor in breast cancer through mechanisms similar to CDH1." (PMID 23717195, 2013). "The disruption of CTCF in breast cancer cells correlated with the incorporation of repressive histone marks such H3K9me3 and H3K27me3 as well as with aberrant DNA methylation patterns." (PMID 22277129, 2012). "We show that CTCF co-localises with key transcription factors in breast cancer cell lines and that these co-bound regions are likely to be functional." (PMID 22142239, 2011). "Our data suggest a positive, pro-transcriptional role for CTCF in ER-mediated gene expression in breast cancer cells." (PMID 22142239, 2011). "Further, we also analyzed the role of CTCF-regulated hTERT expression on SFN-induced apoptosis in breast cancer cells." (PMID 20625516, 2010). "Depletion of CTCF using siRNA reduced the SFN-induced down-regulation of hTERT mRNA transcription in these breast cancer cells." (PMID 20625516, 2010). "In contrast with CTCF down-regulation, we found an elevated expression of hTERT mRNA in both human breast cancer cells in response to CTCF siRNA treatment." (PMID 20625516, 2010). "CTCF gene knockdown using antisense constructs shows inhibition of K562 cells differentiation and apoptotic cell death in breast cancer cell lines." (PMID 20119526, 2009). "Our results showed that CTCF is expressed in both the nuclei and cytoplasm of the malignant cells; nuclear expression was detected in 41% of breast cancer cases and cytoplasmic expression in 77%." (PMID 15354217, 2004). "CTCF is a potential target gene because it has been mapped to the smallest region of overlap at 16q in breast cancer (16q22.1)." (PMID 15354217, 2004). "In the present study, protein expression of CTCF has been studied immunohistochemically (IHC) to evaluate its possible role in breast cancer as well as to assess its prognostic value." (PMID 15354217, 2004).
breast carcinoma (continued). "We used an online database (ChIPBase v2.0) to predict the transcription factors for ZNF582-AS1, chr19:56, 393, 312-56, and 414, 800 (GRCh38/hg38), and the online tool suggested five potential candidates in breast cancer cell lines, namely CTCF, KDM5B, HIF1A, ARNT, and NRF1." (PMID 35681777, 2022). "Following Torin1 treatment at 25 nM, both CTCF+/− and CTCF-low MCF10A PDX lines were markedly sensitive to these low concentrations, being significantly more repressed in their ability to invade than the trio of breast cancer cell lines carrying higher CTCF levels." (PMID 36037342, 2022). "CTCF can also affect breast cancer development by regulating target genes." (PMID 35954396, 2022). "Indeed, they found that experimentally decreasing levels of CTCF protein in breast cancer cell lines resulted in increased apoptosis whereas CTCF overexpression afforded partial protection against cell death." (PMID 33411704, 2021). "Additionally, CTCF has also been suggested to have oncogenic potential, as increased expression was related to tumorigenesis within several breast cancer cell lines and tumor samples." (PMID 34065345, 2021). "Although the role of CTCF and EGR1 in breast cancer cell proliferation are more well-established as compared to their functions in metastasis, this study supports metastasis suppressor roles for CTCF and EGR1 in breast cancer by acting as positive regulators of NME1 transcription." (PMID 33436746, 2021). "It has been hypothesized that CTCF could enhance tumorigenesis through the inhibition of pro-apoptotic protein BAX, which was increased after CTCF knockdown in breast cancer cell lines." (PMID 34065345, 2021). "These authors proposed that CTCF overexpression may be a compensatory mechanism that evolved as a selective advantage to promote breast cancer cell survival by impeding apoptosis." (PMID 33411704, 2021). "Interestingly, Docquier and colleagues previously noted variable levels of CTCF protein abundance in breast cancer cell lines and normal breast tissues when detected by a C-terminal CTCF polyclonal antibody (Abcam)." (PMID 33411704, 2021). "CTCF phosphorylation at threonine (T) 374 and serine (S) 402 has been observed in breast cancer." (PMID 35011637, 2021). "Depletion of the CTCF gene decreased proliferation and induced apoptosis of breast cancer cells." (PMID 31245293, 2019). "Interestingly, in addition to CTCF sites, accessibility was altered for breast cancer-specific transcription factors." (PMID 30139998, 2018). "In breast cancer cells, PARP1 associates with active chromatin marks, CTCF, and DNase hypersensitivity sites, supporting the idea that CTCF PARylation could preferentially associate with active chromatin marks in the EBV genome." (PMID 29976663, 2018). "Previous work in human breast cancer cell lines showed that decreased CTCF PARylation is accompanied by pronounced changes in cofactor interactions within CTCF complexes and destabilization of specific CTCF-dependent chromatin boundaries, resulting in epigenetic silencing." (PMID 29029387, 2017). "The results of the present study suggested that the CTCF/NF-κB pathway might be involved in the development of breast cancer." (PMID 29212169, 2017). "Furthermore, the effects of CTCF on cell proliferation and migration were investigated through the overexpression or knockdown of CTCF in breast cancer cells." (PMID 29212169, 2017). "In breast cancer, Hi-C and GWAS have been combined to identify risk loci, including the protein-coding genes IGFBP5, KLF4, NSMCE2, and MYC, and the lncRNAs DIRC3, PVT1, and CCDC26, which are associated with CTCF." (PMID 29149895, 2017). "Thus, our in vivo results were consistent with those observed in vitro, further confirming that CTCF suppresses the tumorigenicity of breast cancer cells." (PMID 29212169, 2017).
breast carcinoma (continued). "In contrast, some studies have suggested that CTCF may function as an oncogene in breast cancer and acute lymphoblastic leukemia (ALL)." (PMID 28977939, 2017). "In addition, CTCF levels in breast cancer lesions were significantly lower than those in peritumoral tissues." (PMID 29212169, 2017). "Moreover, immunohistochemical (IHC) analysis showed that the CTCF protein was downregulated significantly in breast cancer tissues (n = 66) compared with peritumoral tissues (n = 30) and fibroadenoma (n = 30) (P < 0.01)." (PMID 29212169, 2017). "In agreement with previous studies in other human cancers, we found that CTCF might inhibit cell proliferation in breast cancer cells." (PMID 29212169, 2017). "Furthermore, CTCF overexpression resulted in the inhibition of proliferation, migration, and invasion, while CTCF knockdown induced these processes in breast cancer cells." (PMID 29212169, 2017). "In addition, ERα positive breast cancer cells overexpress miR-375 concomitantly with promoter DNA hypermethylation and CTCF depletion." (PMID 26983574, 2016). "We tested this on the breast cancer cell line MCF7 for which sequence data from both input material as well as multiple ChIPseq experiments for a number of DNA-associated proteins (ER, EGR1, GATA3, CTCF, MAX, and EP300) are available." (PMID 25887352, 2015). "Indeed, as we described in breast cancer cells, promoters and CTCF sites shared common features of epigenetic change, whereas enhancers displayed different behavior in prostate cancer cells." (PMID 24916973, 2014). "Furthermore, our data indicates that both CTCF and Nucleolin are PARlated in hESCs and PARlated CTCF displays different affinities for its interaction partners, consistent with previous reports in human breast cancer cell lines." (PMID 22879976, 2012). "In terms of response to cancer therapy, the insulator protein CTCF mediated the down-regulation of telomerase in response to sulforaphane exposure, a compound that has histone deacetylase inhibition activity, in human breast cancer cells." (PMID 22984562, 2012). "Because CTCF has been proposed to protect genomic regions against DNA methylation, we decided to evaluate the presence of this factor using a ChIP assay in cells from normal breast tissue and from two breast cancer samples." (PMID 22277129, 2012). "It is currently unknown what the global role of CTCF is in estrogen and tamoxifen-mediated gene transcription in breast cancer cells." (PMID 22142239, 2011). "Epigenetics have been implied in miR-375 regulation in breast cancer cells, where local depletion of DNA methylation and H3K9me2 and dissociation of the transcriptional repressor CTCF leads to miR-375 upregulation and subsequent activation of estrogen receptor α." (PMID 22132151, 2011). "In addition, CTCF siRNA experiments clearly demonstrated that depletion of CTCF restores the SFN-induced down-regulation of hTERT mRNA transcription in these breast cancer cells." (PMID 20625516, 2010). "Therefore, we provide several lines of evidence that SFN-mediated hyperacetylation facilitates the binding of various hTERT transcription repressors such as MAD1 and CTCF to the hTERT control region in breast cancer cells." (PMID 20625516, 2010). "Moreover, CTCF protein level was found to be elevated in breast cancer cell lines and tumors when compared with normal counterparts, also not suggesting that CTCF is a tumor suppressor gene." (PMID 20119526, 2009). "The role of CTCF in cancer has previously been studied in some human tumours; however, its role in breast cancer is still unclear." (PMID 15354217, 2004). "Collectively, these results indicate that breast cancer cells may utilize CTCF and EGR1 to drive Nm23-H1 expression and suppress the invasive phenotype, whereas the downregulation of these proteins in aggressive breast cancers potentially contribute to cancer metastasis." (PMID 33436746, 2021).
breast carcinoma (continued). "They hypothesized that increased levels of CTCF may protect breast cancer cells from apoptosis." (PMID 33411704, 2021). "Furthermore, we found that genes highly correlated with intra-domain BRCAgained CTCF sites are enriched for the essential genes identified using CRISPR-screen data from the breast cancer cell line T47D, suggesting that gained CTCF is involved in cancer functions." (PMID 32933554, 2020). "However, the exact role of CTCF in breast cancer is unclear." (PMID 29212169, 2017). "CTCF not only provides boundaries for accessible and 'protected' transcriptional blocks, but may also influence the actual binding of ER to the chromatin, thereby modulating the estrogen-mediated gene expression changes observed in breast cancer cells." (PMID 22142239, 2011). "However, a study of the CTCF mRNA level in breast carcinoma revealed no significant tumor-associated loss or decrease in expression, and therefore CTCF is unlikely to be a tumor suppressor gene targeted by the 16q22.1 loss in breast cancer." (PMID 20119526, 2009). "In this study, we have reported that PRMT5 is upregulated under hypoxia via CTCF, and its upregulation is essential for EMT and invasion of hypoxic breast cancer cells." (PMID 41150697, 2025). "In breast cancer cells, BAP18 interacts with the BPTF-SMARCA1 complex to facilitate CTCF recruitment to ERα, thereby promoting promoter-enhancer looping and ERα target gene expression." (PMID 41381516, 2025). "This correlation was confirmed in the mouse genome and in breast cancer cells, TFIIIC co-immunoprecipitates with CTCF to possibly form long-range interactions with CTCF, mediating DNA looping." (PMID 40762516, 2025). "Thus, CTCF displacement particularly impacts in 3D genes, by changing their contact environment through TADs fusion as shown for the 3D down gene DUSP1 whose expression is associated with an increased risk of metastasis and shorter overall survival in breast cancer." (PMID 38565950, 2024). "According to previous studies, high expression of SYNJ2 was correlated with hepatocellular tumorigenesis via the CTCF/POLR2A-SYNJ2 axis and with metastasis of glioma and breast cancer through regulating the formation of lamellipodia and invadopodia." (PMID 35581615, 2022). "We validated these findings in TGFβ-treated HMLE mammary epithelial cells and additionally found that mesenchymal breast cancer cell lines MDA-MB-231 and Hs578t cells have a lower CTCF protein expression than epithelial breast cancer cell lines MCF7 and SKBR3." (PMID 35008373, 2022). "A large number of factors were discovered that bind within 10,000 bases of the ACBD3 transcription start site across all tissues, and some of these stand out as having roles in breast cancers, including NOTCH1-NICD, CDK9, CTCF, and CEBPB." (PMID 36012147, 2022). "Since CTL MCF10As are mostly noninvasive, we compared the changes in invasiveness of our CTCF+/− MCF10A cells and PDX cell lines to the well-characterized breast cancer cell lines: MDA-MB-231, MCF7, and SKBR3." (PMID 36037342, 2022). "Here, we choose three CTCF ChIP-seq experiments (HMEC + Broad + CTCF, HMEC + Broad + EZH2 and HMEC + UW + CTCF) and three DHS ChIP-seq experiments (MCF-7, MCF-7+Hypoxia_LacAcid, T-47D), all related to the breast cancer." (PMID 35672401, 2022). "CTCF has been reported to repress oestrogen-induced gene transcription by hampering ESR1 chromatin binding and enhancer-promoter interaction in breast cancer cells." (PMID 36199058, 2022). "We identified a group of TFs that showed L1-derived binding almost exclusively in MCF7 breast cancer cells, including ESR1, CTCF and MYC." (PMID 34070697, 2021).